TNF (tumor necrosis factor)
Diseases named in the same sentence as TNF in open-access papers (continued):
Sharing a sentence is not in itself a finding about the gene and the disease.
Insulin resistance (continued). "In adipose tissue from obese mice, ATMs are the main source of inflammatory mediators, such as IL-6 and tumor necrosis factor-α (TNF-α), which can induce insulin resistance by inhibiting the tyrosine phosphorylation of insulin receptor substrate (IRS)." (PMID 34716308, 2021). "Various circulating cytokines, e.g., interleukin 6 (IL−6) or tumor necrosis factor-alpha (TNF-alpha), seem to be culprits in exacerbating insulin resistance in pregnancy." (PMID 34360631, 2021). "TNF-α is also interconnected with obesity, T2DM and insulin resistance, where its expression is upregulated in obese individuals." (PMID 33716966, 2021). "In adipose tissue, adipokines, including monocyte chemoattractant protein-1, tumor necrosis factor-alpha (TNF-α), and interleukin 6 (IL-6), play major roles in inflammation in type 2 diabetes, insulin resistance, cardiovascular diseases, and cancer." (PMID 34812408, 2021). "We found that exercise significantly improves HFD-induced glucose intolerance and insulin resistance, along with an increase in acetylcholine level, ChAT activity, and PKC activity, and decrease in TNF-α level in the system and the spleen from HFD-fed mice." (PMID 34717724, 2021). "ROS-induced insulin resistance is mediated by some mechanism, including c-Jun N-terminal protein kinase (JNK) activation, tumor necrosis factor-alpha (TNF-α) increment decrease glucose uptake." (PMID 34371867, 2021). "Both a decrease in the proinflammatory cytokines tumor necrosis factor-α (TNF-α) and IL-6 and an increase in the secretion of the anti-inflammatory cytokine IL-10 slowed systemic inflammation and insulin resistance in mice." (PMID 34016950, 2021). "The increased secretions of multiple proinflammatory cytokines and chemokines, such as IL-6, TNF-α, IL-1β, and monocyte chemoattractant protein-1 (MCP-1) in adipose tissue are involved in insulin resistance." (PMID 34043673, 2021). "The anti-inflammatory property of IL-6 is shown by way of an inhibitory effect on TNF-α, IL-10, and IL-1β, to protect against TNF-induced insulin resistance." (PMID 33614663, 2021). "Adipocyte hypertrophy generally increase the expression of pro-inflammatory cytokines including tumor-necrosis factor-α (TNF-α), IL-6, and IL-1β in the human patients with insulin resistance." (PMID 34484126, 2021). "Hypertrophic adipocytes secrete inflammatory cytokines, such as tumor necrosis factor-α (TNF-α) and monocyte chemoattractant protein (MCP-1), leading to insulin resistance." (PMID 34203569, 2021). "Although the signaling pathway responsible for TNF-α induced uric acid production is unclear, we have previously shown the inhibitory effect of BLEx on TNF-α-induced insulin resistance in C2C12 myoblasts, in which TNF-α signaling was blocked by BLEx." (PMID 34961109, 2021). "The outcome reveals, for the first time, a link of target pharmacology to insulin resistance, dysglycemia, blood pressure, dyslipidemia, and low-grade inflammation—including key mediators of insulin resistance, TXNIP, and TNFα." (PMID 34371884, 2021). "Maternal fasting glucose, insulin, homeostatic model assessment of insulin resistance (HOMA-IR), leptin, TNF-alpha, C-reactive protein, adiponectin, and lipids are measured by trained staff at each research site, following the established protocols." (PMID 33827659, 2021). "A myriad of inflammatory cytokines including TNF-α, IL-6, and C-reactive protein (CRP), are increased in skeletal muscle under conditions of insulin resistance." (PMID 33922918, 2021). "Adipose tissue also releases large amounts of tumor necrosis factor (TNF)-alpha, which is at least partially responsible for developing insulin resistance in obese people." (PMID 33540682, 2021). "Insulin resistance state affect IFN-α efficacy mainly through downregulating IFN-γ, TNF-α and multiple cytokines." (PMID 34901094, 2021).
Insulin resistance (continued). "Various kinases, which can be stimulated by TNF-α and IL-6, such as Jun NH2-terminal kinase (JNK), an inhibitor of NF-κB kinase (IKK) and protein kinase C (PKC) are candidates that can mediate insulin resistance." (PMID 34069933, 2021). "Moreover, ginsenoside Re could promote insulin secretion, stimulate cannabinoid type 1 receptor (CB1) and CaMKK β to activate the AMPK signaling pathway, inhibit insulin resistance induced by TNF-α, and improve blood glucose uptake and diabetic nephropathy, so as to exert the goal of anti-diabetic." (PMID 34771066, 2021). "We constructed a cellular model of TNFα-induced insulin resistance in 3T3-L1 cells to establish the mechanism of DHM in relieving HFD-induced inflammation and insulin resistance." (PMID 34650665, 2021). "Local inflammation due to residential macrophages plays a key role in liver insulin resistance due to HFD diet consumption, exemplified by increased TNF-α and synchronously reduced PPARγ expression in HFD-fed mice in this study." (PMID 34803738, 2021). "Significant correlations were detected between changes in the majority of atherogenicity and insulin resistance markers such as CRI-I, CRI-II, TyG index, AC, LCI, triglyceride to HDL-C ratio, and AIP and serum inflammatory status as measured by TNF-α (ng/L)." (PMID 34742318, 2021). "ROS-caused oxidative stress stimulates the secretion of inflammatory cytokines (such as interleukin-6 (IL-6) and tumor necrosis factor (TNF)-alpha) and adipokines, which leads to insulin resistance and other metabolic disorders." (PMID 33799840, 2021). "TNF-α induces insulin receptor substrate 1 (IRS-1) serine phosphorylation, downregulating insulin action and linking inflammation to insulin resistance in pregnancies." (PMID 34769262, 2021). "Results from our in vitro experiments also showed that TNFα induced the NF-κB and JNK-1 activation and insulin resistance in 3T3-L1 cells." (PMID 34650665, 2021). "Adipose tissue secretes cytokines like tumor necrosis factor alpha (TNF-alpha), which induces the production of free fatty acids, decreases adiponectin synthesis, disrupts insulin signaling, and ultimately leads to insulin resistance." (PMID 34123557, 2021). "Additionally, 48.7% of the entire cohort of tested RA patients showed insulin resistance, a metabolic condition that might be the reflection of the background RA-related inflammatory state: previous studies have in fact highlighted that TNF-α inhibition improves the HOMA-I in patients with RA." (PMID 34579044, 2021). "Such macrophages predominantly present the M1 pro-inflammatory phenotype and promote inflammation by releasing tumor necrosis factor alpha (TNF-α) and interleukin 6 (IL-6), thus contributing to insulin resistance." (PMID 34884217, 2021). "Following the infiltration of CD8-positive cytotoxic T cells and the phenotypic change to M1 macrophages, inflammatory adipokines including TNF-α, IL-6, and RETN are produced, leading to insulin resistance." (PMID 34884703, 2021). "The ZS-Ag-NPs treatment significantly decreased insulin resistance and metabolic inflammation-related LTB4-R, TNF-α, IL-4 and STAT-6 mRNA levels." (PMID 34685001, 2021). "The expressions of TNF-α and AKT, which were well known to be insulin resistance-related factors in adipocytes, were evaluated to observe the mechanistic effect for the insulin sensitivity by L. plantarum extracts." (PMID 33954196, 2021). "Omentin-1 serum concentration is negatively correlated to BMI, insulin resistance index (HOMA-IR), fasting insulin, plasma glucose, leptin, TNFα and IL-6." (PMID 33799622, 2021). "Inflammatory markers involved in metabolic syndrome (TNF-α, IL-1, IL-6, PAI-1) can upregulate periodontal disease when a persistent periodontal inflammation can exacerbate systemic inflammation, insulin resistance and endothelial dysfunction." (PMID 34187434, 2021).
Insulin resistance (continued). "At the same time, an increase in the production of pro-inflammatory TNF-α playing a central role in the JNK1-mediated development of inflammation and insulin resistance of adipose tissue was observed in the white fat of rats treated with Trp." (PMID 33670919, 2021). "Conversely, by targeting the ADAM17/TNF axis, overexpression of TIMP-3 in mouse macrophages reduced adipose inflammation, insulin resistance and nonalcoholic fatty liver disease, other than reducing atherosclerotic plaques in a mouse model of atherosclerosis." (PMID 33579029, 2021). "T2DM is associated with long-term chronic low-grade inflammation characterized by an increase in some inflammatory markers, such as TNF-α, IL-6, and CRP, contributing to insulin resistance and the pathogenesis of T2DM." (PMID 34955840, 2021). "Pro-inflammatory factors, like IL-6, TNF-α, MCP-1, also aggravated glucose dysregulation and inhibited normal insulin signaling, resulting in insulin resistance (IR)." (PMID 33778016, 2021). "Results from us in vitro experiments also showed that TNF‐α induced the NF‐κB and JNK‐1 activation and insulin resistance in C2C12 cells." (PMID 34676967, 2021). "In contrast to sham surgery, RYGB reduced body weight, improved glucose tolerance and insulin resistance, and decreased serum levels of LPS, IL6 and TNFα." (PMID 34290269, 2021). "Evidence indicates that TNF-α and IL-1β facilitate insulin resistance development by elevating blood insulin and HDL cholesterol levels 3 and insulin resistance suppresses keratinocyte differentiation, resulting in persistent proliferation." (PMID 33391503, 2021). "Studies have shown that TNF-α, monocyte chemoattractant protein-1 (MCP-1), C-reactive protein (CRP), ILs and other inflammatory factors can promote skeletal muscle insulin resistance." (PMID 32082422, 2020). "Previous studies showed that TNF-α induced the expression of NOX3, promotes ROS production, activates the JNKs signaling pathway, and produces insulin resistance in the HepG2 cells." (PMID 32425786, 2020). "Higher circulating C-reactive protein, interleukin 6, and tumor necrosis factor alpha have been reported in PCOS which, through various mechanisms, can contribute to adipocyte dysfunction, insulin resistance, and type 2 diabetes." (PMID 31952348, 2020). "Macrophages stimulate the production of cytokines with proinflammatory activity, such as interleukin (IL)-1β, IL-6, and tumor necrosis factor-alpha (TNF-α), which also play roles in the development of insulin resistance." (PMID 33316948, 2020). "In order to better link the changes in intestinal flora of PCOS model rats with insulin resistance, we measured the serum concentration of HS-CPR, IL-6, and TNF-α." (PMID 32973686, 2020). "Insulin resistance leads to increased release of free fatty acids (FFA) and release of various inflammatory cytokines including tumor necrosis factor- α (TNF-α), interleukin 6 (IL-6), leptin, and resistin." (PMID 33330100, 2020). "Oxidative stress-induced impairment of BLVRA increased accumulation of amyloid beta (Aβ) and tumor necrosis factor-alpha (TNF-α), that greatly contribute to the onset of brain insulin resistance along the progression of Alzheimer’s disease pathology." (PMID 32290442, 2020). "The 30%-T or 5%-L mice had lower plasma glucose, insulin, glucose area under the curve (AUC), homeostatic model assessment of insulin resistance (HOMA-IR), alanine transaminase, triglyceride, and tumor necrosis factor alpha levels." (PMID 32425738, 2020). "Subjects with 25(OH)D deficiency were predominantly females and presented higher body weight, body mass index, waist circumference, triglycerides and Tumor Necrosis Factor-α (TNF-α), and higher insulin resistance." (PMID 32178228, 2020). "The increased production of pro-inflammatory cytokines such as “TNF- α, IL-1β, IL-6, and MCP-1” in turn, triggers chronic inflammatory reactions and enhance insulin resistance." (PMID 33329380, 2020).
Insulin resistance (continued). "The levels of pro-inflammatory cytokines (TNF-α, IL-1β and IL-6) and the expression of TLR4 were downregulated (P < 0.05), while the insulin resistance index, HOMA-IR showed improvement by GP treatment (P < 0.05)." (PMID 32024509, 2020). "In terms of pre-diabetes, a number of studies have reported the effects of quercetin on TNF-α activity, where quercetin showed to ameliorate TNF-α pro-inflammatory cytokine induced insulin resistance in skeletal muscle tissue." (PMID 32694996, 2020). "In pregnant women, excessive fat mass increases the circulating levels of pro-inflammatory cytokines, IL-6, and tumor necrosis factor- α (TNF-α), among others, which further accentuates pregnancy-induced insulin resistance." (PMID 33374585, 2020). "The excess of adipose tissue increases secretion of inflammatory cytokines such as TNF-alpha and IL-6 that inhibit phosphorylation of insulin receptors (IRS-1), promoting insulin resistance." (PMID 32599690, 2020). "Among other “adipokines,” IL-6 and TNF-α are also shown to promote CMS, thus, dysregulation of adipokine synthesis and release plays a critical role in insulin resistance." (PMID 33344519, 2020). "The persistent increase in chemokines and inflammatory cytokines such as TNF-α, INF-γ, and IL-6 leads to progression of insulin resistance in one hand and of DNP to end-stage renal disease and kidney failure on the other." (PMID 33442388, 2020). "Plasma serine protease activity was positively correlated with body mass index, hemoglobin A1c, homeostasis model assessment-insulin resistance index (HOMA-IR), tumor necrosis factor-α, and negatively with adiponectin concentration." (PMID 32015418, 2020). "In addition, proinflammatory molecules such as tumor necrosis factor (TNF)-α and galectin-3, which are produced by adipose tissue and induce insulin resistance, and interleukin (IL)-1β, which impairs β cell function, may also cause metabolic dysfunction in distant tissues." (PMID 32411724, 2020). "There is considerable evidence that inflammatory cytokines like tumor necrosis factor (TNF)-α, interleukin (IL)-1β, and IL-6 not only induce systemic insulin resistance, but also influence lipid metabolism." (PMID 31620886, 2020). "Supplementation with vitamin D in obese adolescents resulted in decrease of insulin resistance, while levels of inflammatory markers [CRP, TNF–α, IL–6] remained unchanged." (PMID 32326621, 2020). "Oxidative stress, mitochondrial dysfunction, accumulation of intracellular lipid derivatives, and inflammation (via IL-6 and TNFα) contribute to decreased activation of signaling molecules, including PI3K and AKT, leading to insulin resistance." (PMID 32802136, 2020). "Pro-inflammatory cytokines, such as tumor necrosis factor-alpha (TNF-α), reduce the insulin-stimulated insulin receptor and IRS-1 tyrosine phosphorylation, resulting in impaired insulin action and induction of insulin resistance." (PMID 31906278, 2020). "The production of TNF-α and IL-6 cytokines by macrophages leads to increased serine phosphorylation of insulin receptor substrate-1 (IRS-1), resulting in insulin resistance in the muscle and liver." (PMID 33105775, 2020). "Deletion of VEGFA in WAT leads to little or no change in the expression of inflammatory markers that contribute to systemic insulin resistance, such as EGF-like module-containing mucin-like hormone receptor-like 1 (Emr1), TNF-α, and MCP-1." (PMID 32265845, 2020). "Interestingly, our group and others have provided cumulative findings showing that persistent Th1 and Th17 cytokine levels which include tumor necrosis factor-α (TNFα), interleukin-1 (IL-1), IL-6 and IL-17 exacerbates insulin resistance which may ultimately lead to cardiovascular complications." (PMID 32907543, 2020). "What is more, increased release of tumor necrosis factor α (TNF-α), interleukin 6 (IL6), and monocyte chemotactic protein 1 are all found to be responsible for the development of insulin resistance." (PMID 33042976, 2020).
Insulin resistance (continued). "Indole-3-acetic acid also reduced fasting blood glucose levels and improved insulin resistance as well as macrophage infiltration and expression of MCP-1 and TNF-alpha." (PMID 32717871, 2020). "Besides, deteriorated metabolic status influences elevated levels of inflammatory cytokines such as interleukin 6 (IL-6), tumor necrosis factor alpha (TNF-α), C-reactive protein (CRP), and leptin hormone, which may be implicated in insulin resistance and tumor development." (PMID 33238496, 2020). "Adiponectin, leptin, resistin, tumor necrosis factor alpha (TNF-α) and interleukin 6 (IL-6) are produced, being tied to insulin resistance and hyperinsulinemia, thus directly or indirectly affecting AD risk." (PMID 32503113, 2020). "Meanwhile, after resveratrol supplementation, the decreased level of insulin resistance, ALT, AST, LDLC, TC, and TNF-α were showed in NAFLD patients." (PMID 32477116, 2020). "According to the KEGG results, an integrated pathway was constructed by combining the key pathways in the treatment of DM, including PI3k-Akt, TNF, HIF-α, insulin resistance, FoxO, toll-like Ras, Rap-1, AMPK, MAPK, and cAMP signal pathways." (PMID 32595730, 2020). "Additionally, the deficit of miR-1305 may also result in insufficient inhibition of ACSL6, leading to intensive synthesis of ceramides, and thus linking excess nutrients and inflammatory cytokines (e.g., tumor necrosis factor-α, TNF-α) to the induction of insulin resistance." (PMID 32069846, 2020). "The first proinflammatory cytokine recognized for its involvement in pathogenesis of insulin resistance and T2DM was TNF-α." (PMID 32089876, 2020). "Likewise, TNF-α is a proinflammatory cytokines also produced by the placenta, apart from skeletal muscle, aiming to exacerbate insulin resistance; it seems to play a significant role in the development of insulin resistance, with higher expression of TNF-α receptors in placenta of GDM women." (PMID 33424775, 2020). "TNFα also is first defined cytokine in NAFLD and induces insulin resistance by activation of NF-κB signaling." (PMID 31083413, 2019). "It is reported that proinflammatory cytokines TNF-α and IL-6 produced by HFD were able to induce insulin resistance." (PMID 31861309, 2019). "TNF-α induces the phosphorylation of insulin receptor substrate 1 (IRS-1) on serine instead of tyrosine residues, promoting insulin resistance." (PMID 31331342, 2019). "Visfatin-induced inflammation and insulin resistance were regulated by JAK2/STAT3 and IKK/NF-κB signaling; together with AG490 or Bay 7082, visfatin significantly reduced mRNA levels of IL-6, TNF-α and IL-1β and rescued insulin signaling." (PMID 31396538, 2019). "Fasting plasma glucose, insulin, insulin resistance (HOMA-IR index, IRI), the S-100β protein level, and the inflammatory mediators IL-1β, IL-6 and TNF-α were assessed after surgery (postoperative day (POD) 1 and 3)." (PMID 31092210, 2019). "Essentially, inflammatory signalling interferes with insulin signalling, with TNFα and several stress-related kinases (IκB kinase β (IKKβ), c-Jun N-terminal kinase (JNK)) being major mediators of insulin resistance." (PMID 31466350, 2019). "On the other hand, exercise training can reduce insulin resistance through GLUT-4 displacement, increased HDL and decreased triglyceride, LDL, and cholesterol, increased adiponectin and omentin 1 and reduced TNF-alpha reduced." (PMID 31105587, 2019). "Obese pre-DM patients showed high values of glucose, insulin resistance (HOMA-IR), C reactive protein (CRP), nitrotyrosine, tumor necrosis factor-α (TNF-α) and interleukin 6 (IL-6), and low values of insulin (p < 0.05)." (PMID 30845774, 2019). "Non-clinical studies have shown that azilsartan increases the expression of PPARγ and decreases that of tumor necrosis factor-α (TNF-α), a cytokine that reduces insulin sensitivity; therefore, it is expected to improve insulin resistance in clinical settings." (PMID 30943275, 2019).